IL10 (interleukin 10)
Diseases named in the same sentence as IL10 in open-access papers (continued):
Sharing a sentence is not in itself a finding about the gene and the disease.
infection (continued). "As regards as IL-10 immunomodulatory factor, it was increased with age mainly to counterbalance an inflammatory background, and the AAV-LAV-BPIFB4 infection further increased its level, consistent with an anti-inflammatory action." (PMID 35087020, 2022). "Thus, in the current case of vaccinated individuals with previous infection and high basal levels of IL-10, this cytokine could decrease the immune response mediated by T lymphocytes to the vaccine but, on the other hand, polarized it to a strong response mediated by B lymphocytes." (PMID 36052060, 2022). "In the MLN, the percentage of IL-10+ CD8+ T cells, CD4+ T cells and ILCs increased upon infection, while both IL-10+ B cells and myeloid cells remained unchanged between naïve and infected samples." (PMID 35428872, 2022). "Similar to TGF-β, the level of IL-10 was significantly increased at 2 weeks post-infection in mice treated with 40 mM L-GSH, while the level of IL-10 was significantly reduced in 80 mM L-GSH-treated animals, compared to the untreated group." (PMID 35453358, 2022). "Overall, analysis of splenic immune response showed the ratios between IFN-γ/IL-10 and IFN-γ/ IL-4 higher in LmexCen−/− immunized hamsters than in LmexWT infection." (PMID 36463228, 2022). "On the other hand, pDCs reinforced their role as down-modulatory cells, with up to 75% of the cells producing IL-10 and an increased percentage of cells producing TGF-β1 after infection." (PMID 35720410, 2022). "A strong interaction between dietary APS and NE infection was observed in relation to TLR2, IFN-γ, TNF-α, IL-6, IL-10, RORα and Foxp3 (P < 0.05) in jejunum." (PMID 35265068, 2022). "It is worth mentioning that when Css54 and MCP-1 were applied in combination, there was a clear increase in the expression of IL-10 and TNF-α while other cytokines remained at the same level that those presented in the infection group." (PMID 35625251, 2022). "Porcine Tregs have been shown to facilitate viral persistence during infection with porcine reproductive and respiratory syndrome virus (PRRSV) by secretion of IL-10 and subsequent inhibition of Th1-mediated antiviral responses." (PMID 35215216, 2022). "In the present study, the IL-6, IL-10 and TGF-β productions varied in their levels of increase at different days post-infection, which is similar to the observation made in a study on T. spiralis infection in large white pigs." (PMID 33639942, 2021). "At 7-weeks post-infection the human cytokines IFN-γ, TNF-α, IL-12p40, IL-10 and IL-13 were elevated in humanized mice infected with HTLV-1, S. stercoralis or with the dual infection, as compared to background controls." (PMID 34314415, 2021). "Using Il10-eGFP-reporter mice (VertX, with genetic background C57BL/6J), the authors observed that 79% of blood NK cells became GFP-positive during acute infection with this bacterium." (PMID 35053151, 2021). "An upregulation in IL10 expression in the presence of HIV and SARS-CoV-2 infections in both Calu-3 cells and PBMCs, in comparison to the other conditions of single infection, was reported." (PMID 34831410, 2021). "Among serum molecules identified in non-neurological and neurological diseases in the acute phase of the infection, 12 (IL-1β, IL-6, TNF, IL-2, IL-7, IL-17A, IL-15, IFN-α, IL-5, IL-13, IL10, and GM-CSF) were shared by both networks." (PMID 33776990, 2021). "A cytometric bead array (CBA) was used to simultaneously determine the level of cytokines IL-6, IL-10, MCP-1, IFN-γ, TNF-α, and IL-12p70 in the serum of uninfected mice and mice infected with T. gondii at six-days post-infection." (PMID 34578186, 2021). "GTP vaccine strains infection alone can enhanced the mRNA expression of IL-1β, TNF-α, IL-6, IL-10, while the expression of IFN-α mRNA is inhibited." (PMID 33827620, 2021). "While TNFα secretion is a part of the hepatic acute phase response after TBI, IL-10 expression post-TBI impairs T-cell immunity, which decreases the ability to fight infection early after TBI." (PMID 34640381, 2021).
infection (continued). "For instance, anti-inflammatory cytokines IL-10 and TGFβ have been shown to mediate persistence of chronic infection in C57BL/6 mice after resolution of initial infection with L. tropica, the species most responsible for recurring LR." (PMID 34169006, 2021). "At both post-infection periods, FICZ increased the numbers of CD11c+ cells expressing IL-12, IL-6, TGF-β and IL-10." (PMID 33936043, 2021). "Infection with HIV has been shown to lead to a switch from Th1 to Th2 cytokines where IL-4 and IL-10 belong." (PMID 35283948, 2021). "Myeloid KLF4 KO mice showed reduced levels of TNF-α, KC and IL-1β and increased levels of IL-10 in BALF and plasma after infection with S. pneumoniae." (PMID 34589087, 2021). "While in rodent models, an increase of IL-4, IL-10 and IFN-γ production was observed by spleen mononuclear cells during early infection, suggesting a mixed Th1/Th2 response." (PMID 34215335, 2021). "Concomitant to the peak of infection, these animals elicited a strong transient type I and III interferon response and induction of the anti-inflammatory cytokine IL10 in the nasal mucosa." (PMID 34029358, 2021). "An analysis performed in the lymph node draining the site of infection revealed an increase of the parasite-specific IFN-Υ production by CD4+ and CD8+ T cells and a decrease in the secretion of IL-10 against leishmanial antigens." (PMID 33673117, 2021). "A number of other immune system modulators such as TGFβ, IL10, and type-I IFN were also inversely regulated between 3 and 7 dpi, suggesting a complex regulation of immunity over the course of infection." (PMID 33865073, 2021). "Retrospective analysis of human samples after an Italian CHIKV outbreak revealed an increase in IL-6 during the acute phase of infection, and low levels of IL-1β, TNF-α, IL-12, IL-10, IFN-γ, and IL-5 that increased as disease progressed to the chronic state." (PMID 34106915, 2021). "A recent pre-print report from a Brazilian research group describes infection of CD4+ T cells by SARS-CoV-2, with subsequent high expression of IL-10 by infected cells." (PMID 33493185, 2021). "We have detected that IFN-γ expression was up-regulated, while IL-10 expression was down-regulated in Ms_Rv0580c infected THP-1 cells, as compared to Ms_pNIT infected THP-1 cells, at 6 h and 24 h post-infection." (PMID 33535567, 2021). "They induce a strong anti-inflammatory response, with increased amounts of IL-10 and TGF-β, further dampening an effective immune response and perpetuating the infection." (PMID 33916346, 2021). "These alternative activated macrophages expressed peaks of arginase-I activity as well as IL-10 and TGF-β production during the 6th and 8th weeks after infection." (PMID 34358055, 2021). "It suggested that after infection with S. japonicum, the JAK/STAT signalling pathway was activated with the increased expression of IL‐10." (PMID 33959966, 2021). "Infection of the BMDMs with MRSA robustly upregulated the secretion of an array of inflammatory mediators that included TNF-α, IL-12, IFN-γ, and IL-10." (PMID 34681611, 2021). "Neutralization of IL-2 increased the numbers of recently activated CD4+CD69+ T cells and memory CD4 and CD8 T cells after three weeks of infection and the numbers of splenic T cells producing IFN-γ, TNF-α and IL-10." (PMID 34869064, 2021). "Furthermore, LVS induced the production of the anti-inflammatory cytokine IL-10 which has been shown to be produced by activated lung DCs early in the course of respiratory tularemia and by regulatory T cells (Tregs) which are present in the lungs as soon as one day post-infection." (PMID 34202420, 2021). "These virulence factors are immunomodulatory and, indeed, infection with the dnj1∆ mutant revealed impaired induction of the cytokines IL-6, IL-10, and MCP-1 in the lungs of mice compared to infection with wild type or complemented strains." (PMID 34566931, 2021).
infection (continued). "Infection with CoPEC has been shown to promote colon tumorigenesis in mouse models of CRC, such as ApcMin/+ mice, AOM-treated il10−/− mice, AOM/DSS-treated mice or ApcMin/+/il10−/− mice." (PMID 33923277, 2021). "T-helper cell (Th1)-type cytokines, such as TNF-α, IL-6 and IL-1β, and Th2-type cytokines, such as IL-10 and IL-4, were differentially expressed in M. fortis and BALB/c mice in the early stage of infection." (PMID 34689797, 2021). "Studies in animal models have found that the interplay of IL-10, IL-12, INF-γ, and TNF-α was crucial to infection control." (PMID 33799892, 2021). "The expression of the anti-inflammatory molecules IL-10, ANXA1, DUSP1, GILZ and HO-1 was significantly increased upon infection." (PMID 34843584, 2021). "Although there is not much increase in fold change of IL12, if we observe minutely, reciprocity in regulation has been observed between IL10 and IL12 at 45–60 min post infection." (PMID 35011356, 2021). "At 12 weeks post-infection, decreased levels of IFN-γ and IL-10 were observed in all groups, in contrast to increased levels of TGF-β observed across most groups, yet without significance (data not shown)." (PMID 34248935, 2021). "To our surprise, we observed similar gene ratios between infection with WT S. Typhimurium and the two T3SS mutants in several cytokine signaling pathways, including interleukin-4 (IL-4), IL-17, and IL-10 signaling pathways (top)." (PMID 34006652, 2021). "The mRNA expression levels of cytokines IL-2, IL-4, IL-6, IL-8, IL-10, IL-12p40, and IFN-γwere relatively different after P1 infection." (PMID 34988138, 2021). "Anti-inflammatory cytokines such as IL10 and IL4 were slightly decreased around day 5-6 pi, when the infected mice succumbed to the infection." (PMID 34447981, 2021). "On the other hand, this inflammatory response was more efficiently regulated in the later stages of the infection, as evidenced by decreased levels of neutrophils, TNF-α, CCL2, and IL-6 and the increases in the regulatory cytokines IL-10 and IL-27." (PMID 34207076, 2021). "Although some studies indicated that IL-4, IL-10, IL-13, and IFN-γ produced by activated T cells in response to infection likely disrupts OC signaling, the RANK-RANKL signaling pathway is central in the differentiation of OCs." (PMID 33735306, 2021). "We show that, at the location of infection (popliteal DLN), control mice challenged with L. amazonensis secrete comparable amounts of parasite-specific IFN-γ, IL-4, and IL-10." (PMID 33673117, 2021). "Suggesting low systemic response, the blood of mice trained 9 weeks contained lower levels of a broad range of cytokines (IL-1β, IL-6, IL-10, IL-12p40, IL-17A, IL-18, IFNγ, TNF, CCL2 and CXCL5) 2 days after infection with L. monocytogenes." (PMID 34603295, 2021). "For having remained below the technique detection limit, we did not interpret the following values: uninfected mice, IL-2, IL-4, IL-10, and IL-17 values of infected mice, as well as IFN-γ, TNF-α, and IL-6 levels at the infection times from 6 to 240 h." (PMID 34660334, 2021). "Again, B. dorei-treatment significantly reduced the levels of IL-1β, IL-6, TNF-α, IL-10, MCP-1 and IP-10 in lung compared with PBS-treated infection mice at day 7 p.i., to a comparable degree relative to the oseltamivi treatment." (PMID 35154087, 2021). "During FMDV infection, the elevated IL-10 level has been widely reported in the serum of FMDV-infected cattle and pigs, with a peak at day 3 or 4 post-infection, which coincides with the development of the clinical disease." (PMID 34960627, 2021). "A different pattern of cytokine production was observed in intestinal samples, with C. rodentium single infection leading to a modest increase in pro-inflammatory cytokines (TNF, IL-6, IFN-γ, and IL-17) and IL-10 in the colon and cecum." (PMID 33440153, 2021).
infection (continued). "However, the most likely explanation for this discrepancy is that IL-10 overexpression in our model is controlled by zinc supplementation; indeed, the levels of IL-10 are normal before zinc supplementation whereas, in other models, IL-10 is likely overexpressed throughout infection." (PMID 34554927, 2021). "Despite some variation between individual mice, BALF samples from LVS- and fpt mutant-infected mice showed significantly elevated levels of IFN-γ, TNF-α, IL-1β, IL-12p70, IL-10, IL-2, and KC/GRO compared to mock infection." (PMID 34202420, 2021). "Significant differences in the balance between IL-10 and IFN-γ production were observed at 10 weeks after infection." (PMID 34248935, 2021). "Upon infection with cytosolic pathogens such as Listeria, IFNAR signaling in these myeloid cells triggers the expression of IL-10, resulting in the inhibition of key bactericidal mechanisms in monocytes and macrophages." (PMID 35087852, 2021). "While IL1R2, IL23R, IL1R1, IL-10, and CCL24 were highly upregulated upon infection of THP-1 macrophages, their expression was barely affected upon infection of primary macrophages." (PMID 34276658, 2021). "After infection by T. cruzi, peritoneal MΦ produced IL-10, TGFβ, TNFα, and VEGF at all of the times evaluated post-infection." (PMID 34832600, 2021). "In the serum, only IL-10 and IL-13 were significantly increased, while in urine IFN-γ, TNF-α, IL-13, IL-1β, IL-22, and IL-10 were significantly increased in by infection." (PMID 34662329, 2021). "The lung homogenates from Nlrp3−/− mice showed significantly higher levels of IL-1β, IL-6, IL-10, IL-12p70, G-CSF, GM-CSF, TNF-α, and RANTES than the wild-type mice on day 3 post-infection." (PMID 34690967, 2021). "There were researches that contradict IL-10’s role in DHF/DSS; where most of the studies have been conducted with heterotypic infection." (PMID 34447698, 2021). "Specifically, IL-10 elevation, but not TGFβ was associated with human infection, whereas the opposite was true in the mouse model, which may be due to a longer duration of infection in human subjects." (PMID 34662329, 2021). "SAH patients, who developed any kind of infection, CVS or chronic hydrocephalus, had significantly higher serum IL-10 levels compared to controls." (PMID 34064048, 2021). "After 48 h of infection with K. oxytoca AD3, the levels of IL-6 and TNF-α in the thymus, lung, spleen, kidney, and liver of mice increased significantly, while IL-10 decreased significantly, which was effectively alleviated via phage therapy." (PMID 34925270, 2021). "On the other hand, as a result of infection, a significant increase of TNF-α was observed in infected and untreated rats with a concomitant reduction of the anti-inflammatory IL-10." (PMID 34829722, 2021). "Infection with LT2 increased levels of IL-8, TNF-α, and IL-10 in the intestine and plasma, and BB12 mildly downregulated them compared to LT2 alone." (PMID 33670419, 2021). "WT-infection significantly upregulated the expression of gamma interferon (IFN-γ), IL-6, IL-10, and CXCL10 (also known as IP-10) in the lungs compared with that in S gene mutants." (PMID 34425707, 2021). "The PLS showed that the levels of GMCSF, Fractalkine, IFNg, ITAC, IL-1ß, IL-2, IL-5, IL-7, IL-8, IL-10, IL-12, IL-17α, IL-21, IL-23, MIP-1ß, and TNFα had higher impact on the separation between the uninfected and the pre-infection cohort." (PMID 33731158, 2021). "Previous studies found an expansion of CD4+ T cells producing IL-17 triggered by uncomplicated P. vivax malaria, which correlates with the number of CD4+ T cells producing IFN-γ, IL-10, and TGF-β in response to infection." (PMID 34128836, 2021). "Measuring the release of 54 inflammatory mediators confirmed the transcriptomic data and revealed sustained production of tolerogenic factors (IL-27, IL-10, IL-1RA, TSLP) despite infection." (PMID 34367171, 2021).
infection (continued). "In vitro infection of monocytes with the DENV, in the presence of sub-neutralizing concentrations of DENV-specific antibodies resulted in increased production of IL-10 and suppression of IFNβ and iNOS." (PMID 33194836, 2020). "In the case of IL10, the NOP phenotype was predicted to show constitutive high activation which was only transiently equaled by the sOP response to infection." (PMID 32595639, 2020). "The cell-free supernatants after post-infection were analysed for the expression of pro-inflammatory cytokines IL-1β, IL-6 and TNF-α and anti-inflammatory cytokines IL-10, IL-12p40, IL-12p70 and IL-4." (PMID 32295519, 2020). "We previously reported that infection of mouse J774 macrophages with live C. trachomatis induces the release of IL-6, TNF, and IL-8, which were inhibited by IL-10." (PMID 32684836, 2020). "Moreover, early post-SAH infections before day 7 may also confound IL-10 levels." (PMID 32106601, 2020). "Thus, our data suggested that cytotoxic T cell capabilities are or maybe progressively lost during chronic Hep-B infection with a concomitant increase in IL-10 production that in turn could further reduce pro inflammatory status contributing to persistence of infection." (PMID 32210950, 2020). "Similar results were found in murine models infected with Plasmodium falciparum or coinfected with Toxocara canis and Toxoplasma gondii that induced an increase in TNFα, IFNγ, IL10 and IL4 brain production following infection with these parasites." (PMID 33322180, 2020). "The previous cytokine profile study following MHV68 infection shows that spleen from infected mice produces a high-level of IL6 and IFN-γ, whereas in vitro infection of naïve splenocytes induces IL16 and IL10." (PMID 32735617, 2020). "In primary microglia activated by infection with Theiler's murine encephalomyelitis virus (TMEV), AEA treatment increased the expression of IL-10 and decreased the expression of the proinflammatory cytokines, IL-12p70 and IL-23." (PMID 32117037, 2020). "In contrast, M2 macrophages are generated in the late stages of infection, terminating the inflammation and repairing damaged tissues, by releasing anti-inflammatory cytokines such as tumor growth factor-β (TGF-β) and IL-10 and removing damaged cells." (PMID 32845931, 2020). "We found obvious enhancement of TNF-α and IL-10 in both spleen and brain, indicating an inflammation status of BALB/c following EBIV infection." (PMID 33597934, 2020). "In order to improve our knowledge of the interaction between the immune system and S. haemolyticus during the infection, we investigated the expression of IL1β, IL4, IL17, IFNγ, TNFα, TGFβ and IL10 by PBMCs infected withS." (PMID 32799619, 2020). "infection, whereas the corresponding early responding genes in SCC cells were IL10, IL1β, IL1α, TNF, CXCL10, CXCL1, HBEGF, IL6, and CSF3." (PMID 31912662, 2020). "The addition of rIL-27 to L. major lysate-stimulated CD4+ T cells collected at the eighth week post-infection from L. major-infected C57BL/6 mice enhances the population of IL-10+ IFN-γ+ CD4+ cells and IL-10+ IFN-γ− CD4+ cells." (PMID 32849534, 2020). "The supernatants from the infected cultures were collected 24 h post-infection and the amounts of IL-12p40, IL-1β, IFN-β, and IL-10 quantified." (PMID 32327653, 2020). "IL-10, IL-4, NO and H2O2 production showed significant enhancement after infection but was observed to be significantly decreased in DHCSA-d and SSG- treated L. donovani at 24 h, 48 h and 72 h." (PMID 32085719, 2020). "The frequencies of splenic CD4+ T cells expressing IFN-γ, IL-10 and TNF-α were found similar in vaccinated and control mice, whereas a reduction of CD4+IL-4+ cells frequency was observed upon infection in vaccinated mice." (PMID 32040500, 2020). "Our results evidenced that during infection in DH82 cells, L. infantum increased 1.4 times IL-12 mRNA expression and L. amazonensis induced 1.8 times more IL-10 mRNA in relation to uninfected control cells." (PMID 32596164, 2020).